ABCG2 (ATP binding cassette subfamily G member 2 (JR blood group))
Diseases named in the same sentence as ABCG2 in open-access papers (continued):
Sharing a sentence is not in itself a finding about the gene and the disease.
gout (continued). "We also report a novel association between another ABCG2 SNP rs10011796 and tophi in people with gout who are of Western Polynesian ancestry." (PMID 28270222, 2017). "In our study, the association between ABCG2 variants and tophaceous disease persisted in people with gout of Western Polynesian ancestry even after adjusting for potential confounders such as highest recorded urate, disease duration and serum creatinine." (PMID 28270222, 2017). "The mechanisms of association between ABCG2 and tophaceous disease in people with gout are currently unclear." (PMID 28270222, 2017). "Two studies, one from Taiwan and one from Aotearoa New Zealand, have implicated ABCG2 in the development of tophi in people with gout." (PMID 28566086, 2017). "In the coming years the possible contribution of rare penetrant functional variants in ABCG2 to gout will be evaluated." (PMID 28566086, 2017). "A genome-wide association study (GWAS) of serum uric acid levels proved that ABCG2 has multiple SNPs in a genomic region on chromosome 4 as associated with urate levels and prevalence of gout." (PMID 28630638, 2017). "Overexpression of ABCG2 has been shown to cause cancer multidrug resistance, while a reduced expression or function is an established cause of hyperuricemia and gout." (PMID 27741279, 2016). "Pharmacogenetic studies implicated the role of ABCG2 in response to widely used medicines and anticancer agents, as well as in gout." (PMID 27741279, 2016). "The top-ranking known urate loci was ABCG2, the strongest known gout risk locus, with an effect halved in obese compared to lean men (Pdifflean-obese= 2 x 10-4)." (PMID 25811787, 2015). "Previous GWASs have identified SLC2A9 and ABCG2 loci to be positively associated with serum uric acid levels and gout." (PMID 25634581, 2015). "For example, the variation of C421A in the ABCG2 gene is associated with an elevated risk of gout and has been reported to reduce the plasma membrane expression and the transport function of BCRP protein in the model cells." (PMID 26634205, 2015). "SNP rs2231142 in ABCG2 were excluded from this study since our group and other domestic institutions have clearly clarified consistent association between this site and gout." (PMID 26290326, 2015). "This study is the first to examine the possible role of ABCG2 variants, which have previously been found to be associated with gout, in terms of their genetic susceptibility to gout in the Han Chinese population." (PMID 24857923, 2014). "Both genetic variation in ATP-binding cassette sub-family G member 2 (ABCG2) and intake of fructose-containing beverages are major risk factors for hyperuricemia and gout." (PMID 24476385, 2014). "The ABCG2 126X and 141K alleles are associated with an increased risk of gout, whereas 12M has a protective effect on gout susceptibility in the Han Chinese population." (PMID 24857923, 2014). "Recently, it has been shown that genotyping for only the two dysfunctional variants, 126X and 141K, is sufficient to estimate the severity of ABCG2 dysfunction, which is strongly related to an increased risk of gout." (PMID 24857923, 2014). "A prediction model for gout risk using ABCG2 protein function was established based on the genotype combination of Q126X and Q141K." (PMID 24857923, 2014). "The results suggest that ABCG2 interacts with extra-renal metabolic pathways in a complex manner to regulate SU and gout risk." (PMID 24476385, 2014). "The minor allele of rs2231142 (141 K), that reduces efflux of uric acid by reducing expression of ABCG2, is strongly associated with increased risk of hyperuricemia and gout." (PMID 24476385, 2014).
gout (continued). "The risk of gout was significantly increased by ABCG2 dysfunction, and even a mild dysfunction (3/4 function) conferred an increased risk of gout (OR 2.40)." (PMID 24857923, 2014). "Because gout leads to a significantly impaired quality of life and imposes high life-long medical costs, early genetic testing of the ABCG2 gene for protein dysfunction will help implement risk-management systems for gout." (PMID 24857923, 2014). "The role of ABCG2 as a urate transporter with mutations leading to hyperuricemia and gout was recently confirmed." (PMID 24857923, 2014). "The results suggest that ABCG2 interacts with extra-renal metabolic pathways in a complex manner to regulate serum urate and gout risk." (PMID 24476385, 2014). "As ABCG2 is widely expressed in many tissues other than the renal tubule, it seems likely that the effects of ABCG2 genetic variation on hyperuricemia and gout risk act on other sites of urate metabolism or clearance, most likely gastrointestinal." (PMID 24476385, 2014). "Genetic polymorphisms (421C>A and 376C>T) in the ABCG2 gene have been identified to cause hyperuricemia and gout." (PMID 24287461, 2013). "ABCG2 has been found to be a urate efflux transporter, with increased incidence of both hyperuricemia and gout in association with the Q141K ABCG2 single nucleoside polymorphism, which results in decreased urate transport." (PMID 23967177, 2013). "Severe ABCG2 dysfunction particularly increased the risk of early-onset gout (odds ratio 22.2, p = 4.66 × 10−6)." (PMID 24287461, 2013). "Recently, a significant disease-association for a polymorphic ABCG2 variant (resulting in ABCG2-Q141K) has been observed in gout." (PMID 23166586, 2012). "Genome-wide association scans examining the genetic control of serum urate concentrations have identified two renal urate transporters - SLC2A9 and ABCG2 - that have a strong effect on gout risk in multiple ethnic groups." (PMID 22541845, 2012). "Why this is the case is unclear; however, it is worth pointing out that unexpected heterogeneity in genetic association with gout in the Asia-Pacific region has also been documented at ABCG2." (PMID 21658257, 2011). "Markers in SLC2A9 and ABCG2 genes are strongly associated with clinical manifestation of gout in the German MI Family Study." (PMID 19890391, 2009). "SNPs rs734553 and rs6855911, located in SLC2A9, and SNP rs2231142, known to be a missense polymorphism in ABCG2, were associated with gout (p = 5.6*10−7, p = 1.1*10−7, and p = 1.3*10−3, respectively)." (PMID 19890391, 2009). "The ABCG2 polymorphism rs2231142 remained significantly associated with gout after correction for multiple testing with pcorr = 0.013." (PMID 19890391, 2009). "Studies have shown that the ABCG2 gene encodes a high-capacity urate efflux transporter expressed in the human intestine and kidney, and it has been identified as a key genetic determinant in the pathogenesis of gout." (PMID 40376055, 2025). "Furthermore, rs2231142 (ABCG2) has shown significant associations with elevated uric acid concentrations and gout, factors that have been traditionally associated with an increased risk of hypertension." (PMID 40742006, 2025). "Genetic variants affecting renal and extrarenal urate transporters, such as URAT1, SLC2A9, and ABCG2, play a critical role by determining individual susceptibility to hyperuricemia and subsequent gout through their effects on serum urate reabsorption and excretion." (PMID 41329531, 2025). "Besides causing drug resistance, ABCG2 is also important in uric acid excretion, and mutations in the ABCG2 gene contribute to a genetic susceptibility to gout." (PMID 40362250, 2025). "The frequencies of ABCG2 dysfunctional variants were high among the participants, and they tended to be higher in participants with asymptomatic hyperuricemia than in those with gout." (PMID 38397902, 2024).
gout (continued). "However, in the present research, the most significant SNP in this locus, ABCG2, rs10011796, was associated negatively with gout risk." (PMID 38831441, 2024). "Notably, the integration of the ABCG2 rs2231142 risk locus, a well-established genetic factor in gout pathogenesis, aligns with studies showing its role in elevating serum uric acid levels, thereby exacerbating gout risk." (PMID 39618928, 2024). "ABCG2 allelic variants are associated with different protein activities, drug sensitivities depending on the cell type and the progression and prognosis of lung cancer, leukemia, and lymphoma, and important genetic factors for developing gout." (PMID 38674407, 2024). "Intriguingly, a study of European and Polynesian populations discovered that a prevalent variant in the ABCG2 (rs2231142) was positively associated with hyperuricemia and gout, meaning that populations carrying alleles with this variant had increased uric acid levels and a higher likelihood of gout." (PMID 38831441, 2024). "The most prominent and well-established risk variant is ABCG2 rs2231142 single nucleotide polymorphism (SNP), a missense SNP that could be causally related to at least 10 % of all gout cases." (PMID 39315221, 2024). "Consequently, the dysfunction of ABCG2 leads to elevated levels of uric acid, causing hyperuricemia and gout." (PMID 39621803, 2024). "ABCG2 dysfunction was known to be a risk factor for pediatric-onset hyperuricemia and gout." (PMID 37238926, 2023). "Additionally, a significant association between rs2231142 or rs2054576 of ABCG2 and Korean gout was revealed." (PMID 38060535, 2023). "We believe that ABCG2 rs2231142 T-allele might contribute to the formation of nephrolithiasis through inflammation elicited by hyperuricemia and gout." (PMID 36967798, 2023). "Our finding concurs with the results in previous studies and suggests that the association between the ABCG2 genetic variants may contribute to the formation of nephrolithiasis through inflammation elicited by hyperuricemia and gout." (PMID 36967798, 2023). "The ABCG2 risk alleles have been associated with AP resistance, and it is possible these variants lead to relative hyperuricemia even with urate-lowering AP therapy in patient with gout." (PMID 35726318, 2022). "In addition, they found that the protective effect of SLC22A12 on gout exceeded the pathogenic effect of ABCG2 on gout." (PMID 35922835, 2022). "Studies have shown that HPRT and PRPS1 gene mutations seem to be the main cause of primary gout; SLC22A11 gene mutation is associated with RUE (renal underexcretion) gout; ABCG2 seems to be one of the reasons for the genetic heterogeneity of ROL (renal overload) and RUE gout." (PMID 35922835, 2022). "It has been reported that ABCG2 plays multifunctional roles in human diseases, such as inducing multidrug resistance in cancer treatment, contributing to the risk for hyperuricemia and gout, and overexpressing in resistant acute myeloid leukemia phenotype." (PMID 36555598, 2022). "Our finding suggests that the rs2231142 (G > T) in ABCG2 may increase urate levels and gout risk in Asian and Pacific Islander subgroups compared to EUR." (PMID 34986901, 2022).
gout (continued). "Additionally, a meta-analysis conducted on a multi-ethnic cohort reported that the T allele of the rs22131142 (G > T) in ABCG2 was strongly associated with HU and gout across different ethnic groups and further modulates the severity and gout onset." (PMID 34986901, 2022). "The ABCG2 gene is a well-established hyperuricemia/gout locus that plays a crucial role in renal and intestinal urate excretion; dysfunction of the ABCG2 is a risk factor for hyperuricemia and gout." (PMID 35406626, 2022). "Nevertheless, the results of the current study imply that genotyping for polymorphism at the SLC2A9 and ABCG2 genes may be useful when counselling gout patients about risk of hypertension and the need to take preventative measures." (PMID 35633389, 2022). "Thus, ABCG2 plays a crucial role as an essential renal and intestinal urate exporter, as its dysfunction is associated with abnormal serum uric acid levels and gout/hyperuricemia risk." (PMID 36483739, 2022). "A1CF might, therefore, have synergistic effects on susceptibility to gout with dysfunctional variants of ABCG2, for which further analyses are necessary." (PMID 33517564, 2021). "Specifically, the experimental tool we developed in this study is applicable for screening drugs that promote PM delivery of ABCG2 variants with impaired trafficking; thus, it has the potential to support the development of more effective and personalized therapies for gout patients." (PMID 33634118, 2021). "The functional rs2231142 and the intronic rs1871744 are, in genome wide association studies, correlated with serum level of urate, one of endogenous substrates of ABCG2, the susceptibility of gout, which is caused by hyperuricemia, and response to allopurinol in patients with gout 39-41." (PMID 33531973, 2021). "Recent genomic-wide association studies conducted to determine the cause of these clinical differences have shown that some polymorphisms in ATP-binding cassette G2 (ABCG2) lead to hyperuricemia through renal overload and renal underexcretion and also increase the risk of early-onset gout." (PMID 34207250, 2021). "The ABCG2-Q141K variant, with reduced expression level and function, is present in 15–35% of individuals, depending on the genetic background of the population, and has been shown to significantly affect gout development." (PMID 34855903, 2021). "In addition, we will shed light on newly identified polymorphisms in ABCG2 associated with early-onset gout." (PMID 34206432, 2021). "The common ABCG2 variant Q141K contributes to hyperuricemia and gout risk." (PMID 32488095, 2020). "ABCG2 variants were associated with gout/hyperuricemia in both Asians and Caucasians." (PMID 33087043, 2020). "Moreover, ABCG2 dysfunction was reported as a strong independent risk factor for pediatric-onset hyperuricemia/gout." (PMID 32090094, 2020). "In addition to the common Q141K variant, there are numerous other uncommon and rare missense variants in ABCG2, mostly detected by resequencing ABCG2 exons in people with gout." (PMID 32164793, 2020). "In addition, ABCG2-rs72552713 also increased the risk of gout whereas ABCG2-rs2231137 reduced the risk in Asians." (PMID 33087043, 2020). "ABCG2 is a high-capacity urate exporter expressed in the intestine and kidneys, and ABCG2 dysfunction strongly increases serum urate levels and the risk of gout development." (PMID 32850823, 2020). "ABCG2 gene encodes a urate transporter that influences serum urate concentrations and gout risk." (PMID 32000861, 2020).
gout (continued). "Besides, the ABCG2 rs2231142 allele is strongly associated with early-onset gout, with a sex-specific effect (as men present higher SU levels compared to women), and with a poor response to allopurinol." (PMID 33117824, 2020). "We tested the hypothesis that ABCG2 plays a role in the progression from HU to gout by testing for association of ABCG2 rs2231142 and rs10011796 with gout using HU controls." (PMID 32164793, 2020). "Here, we have focused on the role of ABCG2, the highest risk gout gene, in urate excretion." (PMID 32488095, 2020). "Furthermore, BCRP/ABCG2 plays an important role in the renal and gastrointestinal excretion of urate, whereas the dysfunction of BCRP/ABCG2 has proven to be a major cause of hyperuricemia and gout." (PMID 33008107, 2020). "Furthermore, loss-of-function mutation in ABCG2 rs2231142 (Q141K) is associated with an increased risk of hyperuricemia and gout by decreased renal proximal tubule transport." (PMID 31491937, 2019). "In addition to Q141K, ABCG2 Q126X (c.376C>T), which is common in the Japanese population but rare in other populations, has additionally been identified as a hyperuricemia- and gout-risk allele." (PMID 31003562, 2019). "Furthermore, recent evidence demonstrates that dysfunction of ATP-binding cassette subfamily G member 2 (ABCG2), a high capacity urate exporter, is an important genetic risk factor in gout and hyperuricemia." (PMID 31752990, 2019). "Our findings might support a “Common Disease, Multiple Common and Rare variant” hypothesis for the association between ABCG2 and gout susceptibility in a European population." (PMID 31003562, 2019). "Urate exporter gene (ABCG2) variants have been shown to increase the risk of hyperuricemia and the most common dysfunctional ABCG2 variant—rs2231142a—has been reported to significantly influence the age of onset of gout and is highly associated with familial gout history." (PMID 31652657, 2019). "For gout risk, sex-specific differences for ABCG2 variants have also been described." (PMID 30626429, 2019). "Besides the rs2231142 variant, this study also found that the rs4148155 variant of ABCG2 was associated with gout." (PMID 30899057, 2019). "Furthermore, several ABCG2 variants have shown to be associated with gout risk and high SUA in different populations." (PMID 30621105, 2019). "The enlarged cohort enabled us to reveal that the numbers of non-synonymous variants of ABCG2 could affect the frequency of familial gout, which was inconclusive in our previous study because of the small sample size." (PMID 31003562, 2019). "The ABCG2 gene is a well-established hyperuricemia/gout risk locus." (PMID 30894219, 2019). "Therefore, further studies on clinical risk prediction for gout in terms of rare ABCG2 variants as well as the functional validation of such variants are required." (PMID 31003562, 2019). "The rs2231142 (Arg141Lys) genetic variant at ABCG2 is a common missense genetic variants, and meta-analysis of existing study found the rs2231142 Arg141Lys carriers was associated with 1.73 fold increased susceptibility of gout." (PMID 30899057, 2019). "The human ABCG2 gene consists of 16 exons and 15 introns and is located on chromosome 4q21–q22, a region that showed one of the most significant associations with gout susceptibility in a series of Genome-wide association studies (GWASs)." (PMID 31003562, 2019).